SIRPA (signal regulatory protein alpha)
Diseases named in the same sentence as SIRPA in open-access papers (continued):
Sharing a sentence is not in itself a finding about the gene and the disease.
tumor (continued). "Another immune cell/macrophage gene widely expressed by human tumor cells (mostly hematopoietic ones but also by some types of solid tumors) is CD47, the activation of which triggers an anti-phagocytic mechanism induced by its ligand SIRPA/CD172a." (PMID 36754910, 2023). "An immunodeficient mouse model that lacks mouse T, B and NK cells and that provides phagocytic tolerance (e.g., via SIRPANOD, human SIRPA transgene (SIRPATg), human SIRPA knock-in (SIRPAKI) or mouse CD47−/−) is necessary to prevent rejection of transplanted human immune and tumor cells." (PMID 37296949, 2023). "Therefore, SIRPα inhibitors, such as CD47 analogues or anti-SIRPα antibodies, are proposed as therapeutic agents that promote the phagocytosis of tumor cells by macrophages." (PMID 37999184, 2023). "The results confirmed that the lack of SIRPα in KO mice significantly reduced LLC tumour cell growth in mice." (PMID 36419386, 2023). "Another emerging strategy to impede CD47/SIRPα interactions is the pharmacological inhibition of glutaminyl cyclases, especially glutaminyl-peptide cyclotransferase like protein (QPCTL), which is highly expressed in tumor cells." (PMID 36052078, 2022). "In the tumor microenvironment, cancer cells trick macrophages by expressing CD47, a “don’t eat me” signal, on their cellular surface and protect them from phagocytosis via binding to signal regulatory protein alpha (SIRPα) receptor on macrophages." (PMID 35216342, 2022). "Moreover, treatment of xenografted Burkitt lymphoma cell line Raji with the bsAb strongly inhibited tumour growth in Rag2‐/‐IL2rg‐/‐FSIRPα knock in (SRG) mice, although the treatment effect was similar to the combination of vorsetuzumab and SIRPα mAb." (PMID 35908284, 2022). "These antagonists include 1) monoclonal antibodies targeting CD47 or SIRPα, 2) SIRPα-Fc fusion proteins, 3) bispecific antibodies (BsAb), 4) small molecules to down-regulate CD47 on tumor cells, 5) RNAi and, 6) CD47-chimeric antigen receptor-T cell/Macrophages." (PMID 35418166, 2022). "Given that increased PD1 and SIRPα were observed in ICC patients in the present study, we speculate that anti-CD47 in combination with anti-PD1 may achieve better anti-tumor effects in ICC patients." (PMID 35317832, 2022). "The CD47–SIRPα axis is the most common “don’t eat me” axis, whose neutralization by anti-CD47 or anti-SIRPα antibodies can enhance phagocytic clearance of cancer cells in many preclinical tumor models." (PMID 35158779, 2022). "Ligation of SIRPα by its ligand CD47 limits effector functions and thereby tumor cell elimination." (PMID 35884427, 2022). "SIRPα is expressed on monocytes, MDMs, and MDDCs where it interacts with its ligand CD47, which is expressed on most cells as a “don’t eat me” signal, but is often overexpressed by tumor cells to escape immune checkpoint." (PMID 36077152, 2022). "Furthermore, our results indicate that, of the 10 selective tumor-promoting genes of macrophages, only MMP19 and SIRPα can predict ICB responses in ICCs." (PMID 36158683, 2022). "CD47v limits the ability of macrophages to devour tumor cells by binding to SIRPα, serving as a “do not eat me” signal." (PMID 35214129, 2022). "Therefore, combinations of tumor targeting antibodies with LILRB1 and either CD47 or SIRPα immune checkpoint inhibitors deserve further evaluation in animal models towards clinical application." (PMID 36389667, 2022). "SIRPα and CD68 were not expressed by cancer cells but rather by tumor-associated macrophages (Μφ, TAMs)." (PMID 35406573, 2022). "SIRPα binds to CD47, a receptor frequently overexpressed on cancer cells, and this interaction provides a “do-not-eat-me” signal to prevent phagocytosis, which plays a pivotal role in tumor progression." (PMID 35585990, 2022). "A recent study provided substantial evidence suggesting that blockage SIRPα/CD47 axis could enhance adaptive immunity and prime an anti-tumor cytotoxic T-cell response." (PMID 35874659, 2022).
tumor (continued). "It is worth noting that SIRPα-exosomes can shorten the time required for exosomes to reach the tumor target of CD47 overexpression, and only low-dose SIRPα-exosomes can effectively inhibit the growth of tumor in vivo by blocking CD47-SIRPα, so as to improve the therapeutic effect." (PMID 34973131, 2022). "In the acidic TME, cleavage of the benzoimine bond of the nanobioconjugate released anti-SIRPα and anti-CD47, which blocked SIRPα on the macrophages and CD47 on the tumor cells, thereby eliminating the “don’t eat me” signal and improving macrophage phagocytosis ability." (PMID 34885247, 2021). "It is suggested that tumor cells and/or non-neoplastic cells escaped tumor immunity by expressing PD-L1 and SIRPα." (PMID 34285260, 2021). "Conversely, in the absence of CD8+ T cells, blocking CD47 does not inhibit tumor growth in syngeneic models, and genetic disruption of SIRPα signaling in macrophages did not impair syngeneic tumor growth." (PMID 33925464, 2021). "ATM, SIRPA, and LILRB2 are potential targets in tumor immunotherapy." (PMID 33868359, 2021). "Moreover, the sera from this MC38 tumor-eradicated Sirpα−/− mice directly labeled MC38 cells, suggesting potential acquisition of humoral antitumor immunity in these tumor-eradicated mice." (PMID 34050181, 2021). "Ex vivo Tc cytotoxicity assays further confirmed that Tc isolated from irradiated WT tumors were inert, while those from irradiated Sirpα−/− BMDM-infused tumors were highly cytotoxic and rapidly eliminated respective tumor cells at a low effector: target ratios." (PMID 34050181, 2021). "We and others have reported that CD47 antibodies exhibit anti-tumor activities independent of SIRPα signaling." (PMID 33925464, 2021). "The disparate efficacies of intratumoral Sirpα−/− macrophages vs. CD47-blockade imply that SIRPα-mediated regulation has a component independent of CD47 binding, which likely plays a key role in controlling tumor responses to RT." (PMID 34050181, 2021). "When compared to Vorsetuzumab + KWAR23 treatment, the CD70/SIRPα bispecific antibody demonstrated an enhanced in-vitro phagocytosis of target tumor cells, but there was no apparent difference in in vivo efficacy observed." (PMID 33790906, 2021). "It is reported that a CD47/SIRPα blockade and TIGIT/PVR blockade could elicit significant anti-tumor responses." (PMID 34068552, 2021). "Besides, the binding of CD47 on cancer cells with the inhibitory receptor signal regulatory protein alpha (SIRPα) on TAM suppresses the ability of macrophages to detect and phagocytose tumor cells." (PMID 33947438, 2021). "Programmed death-ligand 1 (PD-L1) and indoleamine 2,3-dioxygenase 1 (IDO1) expression and signal-regulatory protein alpha (SIRPα), forkhead box P3 (FOXP3), and cluster of differentiation 8 (CD8) infiltration were assessed by immunohistochemical studies of 137 tumor tissues from 96 patients." (PMID 34285260, 2021). "We also observed that when nonirradiated tumors were large (>200 mm3), a single dose of 8 Gy IR administered to the primary tumor failed to control the growth of non-irradiated tumors in Sirpα−/− mice." (PMID 34050181, 2021). "Among the differences between tumor milieus comprising Sirpα−/− macrophages and those without Sirpα−/− macrophages, the robust expansion of tumor-infiltrating cytotoxic T cells (Tc) in Sirpα−/− TME after IR was the most striking." (PMID 34050181, 2021). "In this context, a promising recombinant SIRPα molecule fused to the human IgG1 Fc domain (TTI-621) minimally bound to human erythrocytes, thus displaying reduced toxicity in pre-clinical models, and yet efficiently bound to tumor cells." (PMID 34572013, 2021). "Hence, it is possible to restore TAM recognition and phagocytosis of tumor cells and to activate anti-neoplastic immune responses by interfering with the SIRPα-CD47 axis (e.g., by using antibodies to SIRPα and CD47)." (PMID 34178692, 2021).
tumor (continued). "We also engrafted mice with luciferase-expressing KPC cells, and as shown by whole-body imaging, tumor growth was totally controlled by a single dose of 8 Gy IR in Sirpα−/− mice but not in WT mice." (PMID 34050181, 2021). "In addition, tumor type and stage, tumor immune microenvironment and acquired drug resistance, constitute other potential determinants of the efficacy of CD47/SIRPα inhibitors." (PMID 34944850, 2021). "As to its role in tumour development, CD47, which is an ubiquitously expressed surface receptor in all types of cancers, acts as an antiphagocytic “don't eat me” signal, binding to SIRPα on the macrophages and dendritic cells." (PMID 34093795, 2021). "Despite that the initial TILs comprised both Tc and Th cells, Sirpα−/− BMDMs exclusively induced robust proliferation of Tc but not Th cells, a phenomenon mirroring tumor-specific Tc expansion in irradiated Sirpα−/− tumors in vivo." (PMID 34050181, 2021). "Our finding that CD47 blockade failed to recapitulate the phenomenon of tumor eradication by RT-activated Sirpα−/− macrophages, however, strongly argue that SIRPα controls tumor responses to RT via a CD47-independent pathway." (PMID 34050181, 2021). "Similarly, the combination of anti-human SIRPα antibody KWAR23 and tumor opsonizing antibody rituximab can significantly enhance the anti-tumor activity of neutrophils and TAMs." (PMID 34625124, 2021). "The effects of a CD47/SIRPα blockade by azelnidipine were further explored in the MC38 tumor model, which has a large quantity of intratumoral macrophages and was widely used for the CD47 targeted anti-tumor study." (PMID 34068552, 2021). "Our study unveils SIRPα as a master controller of immunity in the TME by directing the post-treatment response toward wound-healing, strengthening immunosuppression, conferring treatment resistance, and ensuring tumor progression." (PMID 34050181, 2021). "Interestingly, there was no functional data showing the role of SIRP in B cells, while SIRPα was reported to be a critical regulator of myeloid cell activation via binding to CD47 and SIRPα/CD47 axis limited the efficacy of tumor-opsonising antibodies." (PMID 35003068, 2021). "Despite the absence of the TDLN, irradiated tumor explants from Sirpα−/− mice exhibited robust expansion of Tc similar to that which occurred in vivo." (PMID 34050181, 2021). "Here, we firstly demonstrated that azelnidipine dually targeting SIRPα and PVR could be a promising anti-tumor modality in cancer immunotherapy." (PMID 34068552, 2021). "Injected cancer cells failed to grow in tumor-eradicated Sirpα−/− mice, suggesting that these mice had acquired long-term antitumor immunity that prevented tumor recurrence." (PMID 34050181, 2021). "Irradiation damages the tumor tissues and increases infiltration and SIRPα expression on MDSCs, and combined with azelnidipine that blocks CD47/SIRPα interaction, it can enhance MDSC cell-mediated phagocytosis of tumor cells, thereby remarkably inhibiting the tumor growth." (PMID 34068552, 2021). "From this perspective, recent approaches are being evaluated: epigenetic reprogramming of M2-like TAMs into M1-like TAMs; increasing phagocytic activity by CD47/SIRPα blockade; engineering Chimeric Antigen Receptors for Phagocytosis (CAR-P) to increase tumor cell killing." (PMID 34276698, 2021). "The induction of PrCR by “eat-me” signals on tumor cells is antagonized by “do-not-eat-me” signals, which bind macrophages SIRPα to inhibit phagocytosis." (PMID 32161718, 2020). "Besides serving as SIRPα liangd to initiate inhibitory signal for macrophage phagocytosis against self cells, CD47 has been shown as a suppressor for tumor metastasis, and targeting it presents an potential and effective therapeutic strategy." (PMID 32576895, 2020).
tumor (continued). "Flow cytometry analysis at 24 h after tumor cell vaccination revealed that SIRPα+ cells consisted of mainly CD11c−CD11b+ non-DC myeloid cell and CD11c+ DC populations, and the latter can be further divided into CD11b+ and CD11b− DC subsets." (PMID 31996683, 2020). "HAB21 potently enhanced macrophage phagocytosis of DLD-1 tumor cells in a dose-dependent manner irrespective of SIRPα genotype with an EC50 of ~ 0.2 nM, consistent with the high affinity binding of hAB21 to both SIRPα v1 and v2 variants." (PMID 33256806, 2020). "Signal regulatory protein α (SIRPα), a transmembrane protein that is predominantly expressed in dendritic cells (DCs) or macrophages, interacts with CD47 that is overexpressed in almost all types of tumor cells." (PMID 32411788, 2020). "Also, it has been shown that SIRPα is highly expressed in human RCC cells, and anti-SIRPα mAbs decreased tumor formation in syngeneic mice." (PMID 32013092, 2020). "In addition, blocking the myeloid checkpoint of Signal regulatory protein alpha (SIRPα)/CD47 has shown to be efficient improving tumor phagocytosis and thus decreasing tumor burden." (PMID 33585220, 2020). "CD47 overexpression may contribute to the immune escape of tumor cells through the inhibition of ADCP, via the binding of CD47 to the signal-regulatory protein alpha (SIRPα) on TAMs." (PMID 31936617, 2020). "In NCI-H1975 tumor model, tumor weight in mice co-treated with VEGFR1-Fc and SIRPα-Fc was 56.08 ± 32.09 mg (P < 0.0001 versus VEGFR1-Fc cohort), while the tumor weight in VEGFR1-Fc group and the control were 412.15 ± 51.19 mg and 818.09 ± 97.57 mg, respectively." (PMID 31829270, 2019). "Here, we revealed the up-regulation of CD47, the negative checkpoint molecule that binds to SIRPα, as an innate immunosuppressive mechanism that limited the anti-tumor effect of VEGF/VEGFR inhibitors." (PMID 31829270, 2019). "Compared with the negative control PBS/liposome, Clo/liposome accelerated the tumor growth of mice treated with SIRPα-Fc." (PMID 31829270, 2019). "CD47 (Cluster of differentiation 47)/SIRPα (signal-regulatory protein alpha), an innate negative immune regulatory axis that transmits “don’t eat me” signal to macrophages and confers tumor cells resistant to immune surveillance." (PMID 31829270, 2019). "Anti-CD47 antibodies or engineered SIRPα–Fc fusion were shown to restore macrophage ability to phagocytose cancer cells and prime cytotoxic CD8 T-cells, leading to the tumor regression in several tumor models and in clinical trials." (PMID 31547627, 2019). "SIRPα is tyrosine phosphorylated and sequestrates SHP2 from IKKß to PI3K regulatory subunit PI3Kp85, resulting in affecting PI3K‐Akt and NF‐κB pathways in the tumor microenvironment." (PMID 30460349, 2018). "In our study, activation of Notch signaling could suppress SIRPα expression and inhibit MIL4 macrophage polarization as well as phagocytosis, which might have important implications in tumor microenvironment." (PMID 30105024, 2018). "SIRPα immunoregulatory activity on myeloid cells is activated by binding of its ligand CD47, and blockade of the pathway may enhance anti-tumor immunity." (PMID 30400822, 2018). "Another benefit of targeting SIRPα on phagocytes rather than CD47 on tumors is the potential for synergy with tumor‐specific mAbs to increase phagocytosis and enhance the anti‐tumor response." (PMID 30460349, 2018). "CC-90002 selectively binds to CD47 expressed on tumor cells, blocks CD47 interaction with signal regulatory protein alpha (SIRPa), a protein expressed on phagocytic cells, which prevents CD47/SIRPa-mediated signaling and abrogates the CD47/SIRPa-mediated inhibition of phagocytosis." (PMID 29312320, 2017). "Studies performed with experimental models of solid tumors including GBM as well as some hematopoietic cancers have shown that blocking the interaction between CD47 and SIRPα with anti-CD47 monoclonal antibodies (mAbs) promotes phagocytosis in vitro and inhibits tumor growth in vivo." (PMID 28076333, 2017).
tumor (continued). "In the context of tumor immunology, tumor cells have been shown to overexpress CD47, an anti-phagocytic signal directed to macrophages to escape from phagocytosis by interacting with Signal Regulatory Protein α SIRPα." (PMID 27671753, 2016). "It should be noted that similar inhibition of tumor growth is observed when irradiating TSP-1 null mice, thus suggesting that anticancer targeting of TSP-1:CD47 interaction would be of a greater relevance than disrupting CD47:SIRPα." (PMID 26578962, 2015). "In addition, tumour cells often overexpress CD47, which — via interaction with signal-regulatory protein-alpha (SIRPα) — inhibits elimination of tumour cells by macrophages." (PMID 23918228, 2013). "Moreover, when developed subcutaneously, tumor induced the deposition of a CCR2 ligand, CCL2 inside IVRs, resulting in the enhancement of antigen uptake by intrathymic Sirpα+ cDCs." (PMID 22815949, 2012). "Furthermore, we established the Hepa1–6 subcutaneous tumor model and treated the tumor with or without anti-SIRPα antibody or PI3K/AKT signaling agonist 740 Y-P." (PMID 40523887, 2025). "Additionally, the anti-tumor activity of CDH17-CAR-NK cells is synergistically enhanced by CD47–signal regulatory protein α (SIRPα) axis inhibitor CV1, likely through augmented macrophages activation and an increase in M1-phenotype macrophages in the tumor microenvironment." (PMID 40487639, 2025). "Thus, hypoxia induced tumor derived exosomal ZEB1 was demonstrated to promote immune evasion and escape from innate immune surveillance in cervical squamous carcinoma cells by modifying the activity of the CD47/SIRPα/STAT3 axis." (PMID 39928285, 2025). "However, the CD47- SIRPα and the PD1-PD-L1 pathways are part of a more complex tumor microenvironment, which does not only include macrophages and T cells, but is also constituted by B cells, dendritic cells, stromal cells, blood vessels, and extracellular matrix." (PMID 40369208, 2025). "Importantly, MUC16 + SKOV3 or Raji tumor cells express negligible levels of SIRPα and do not function as an antigen sink for these antibodies." (PMID 40408355, 2025). "Unlike these studies focusing on tumor control, our research focused on exploring the specific impact of RT and antibodies on antigen presentation, particularly why the combination of RT and anti-SIRPα outperformed anti-PD1." (PMID 40208335, 2025). "The authors also discovered that metastatic tumor cells tend to express the ligand CD47, an important “don’t-eat-me” signal, which may influence the anti-tumor immunity of MRC1+ CCL18+ macrophages via its corresponding receptor SIRPA." (PMID 40191203, 2025). "Interestingly, this phagocytosis rate does not reduce tumor growth for large engraftments, due to a rapid decrease of macrophages in SIRPα−/− mice." (PMID 41296731, 2025). "Immune checkpoints contribute to the malignant progression of tumor by regulating tumor immune microenvironment and promote malignant behaviors such as tumor cell proliferation and metastasis, including programmed cell death 1 (PD-1), poliovirus receptor (PVR), SIRPA and other immune checkpoints." (PMID 41024301, 2025). "Furthermore, the anti–CD47/SIRPα axis not only inhibits local irradiated tumor cells but also inhibits distant non-irradiated tumor cells." (PMID 40835598, 2025). "For this purpose, it has been possible to create vesicles with signal regulatory protein alpha (SIRPα), which, in addition to lowering CD47 levels, increases the secretion of IFN-γ and conditions the infiltration of CD8+ and CD4+ T cells, further avoiding tumor growth." (PMID 38790954, 2024). "However, Nexturastat A did not enhance the antitumor activity of anti-SIRPα despite its modulation of macrophage populations in the SM1 tumor microenvironment." (PMID 38414061, 2024).